MALAT1 (metastasis associated lung adenocarcinoma transcript 1)
Diseases named in the same sentence as MALAT1 in open-access papers (continued):
Sharing a sentence is not in itself a finding about the gene and the disease.
prostate carcinoma (continued). "MALAT1 was overexpressed in human prostate cancer and positively correlated with Gleason score, and cell proliferation and migration were inhibited in DU145 and PC3 cells when it was knocked down." (PMID 38561330, 2024). "In contrast to normal prostate tissues, prostate cancer tissues have been shown to express MALAT-1 abnormally." (PMID 38511067, 2024). "MALAT1 overexpression was shown to be related with markers of poor prognosis in prostate cancer, which includes a high Gleason result, advanced stage of tumor node metastasis, and serum PSA levels that were greater than 20 ng/mL." (PMID 39512820, 2024). "For example, MALAT1 can regulate expression of the androgen receptor and thereby controls proliferation, invasion, and migration of prostate cancer cells." (PMID 38919532, 2024). "This supports the idea that the MALAT-1-miR-320b-AR axis is critical in controlling prostate cancer cell behavior." (PMID 38511067, 2024). "In conclusion, evidence reveals the relevance of MALAT-1 in controlling prostate cancer glucose metabolism and progression." (PMID 38511067, 2024). "Malat1 expression is substantially higher in CRPC than in primary prostate cancer, and knocking it down resulted in decreased cell proliferation, invasion and migration, as well as in an increase in apoptosis." (PMID 38501046, 2024). "Mechanistically, we show that targeting MALAT1 induces DSBs and apoptosis, which makes prostate cancer cells vulnerable to DNA repair inhibitors, such as olaparib, and DNA-damaging agents like doxorubicin." (PMID 37812088, 2023). "Mechanistically, we show that MALAT1 silencing reprograms the homologous recombination (HR) transcriptome and makes prostate cancer cells more vulnerable to PARPi." (PMID 37812088, 2023). "RNA-seq data analyses from the CCLE revealed high expression of MALAT1 in multiple human cancer cell lines, with the highest expression noted in prostate cancer." (PMID 37812088, 2023). "Metastasis-associated lung adenocarcinoma transcript-1 (MALAT1) is a long non-coding RNA highly expressed in various malignancies such as bladder, lung, and prostate cancer." (PMID 36674430, 2023). "Tumors with elevated levels of MALAT1 also show a higher propensity for lymph node metastasis, disease recurrence, and therapeutic failure in patients with prostate cancer." (PMID 37812088, 2023). "MALAT-1, which is overexpressed during prostate cancer progression, was detected in plasma of patients with prostate cancer compared to non-prostate cancer patients." (PMID 37143733, 2023). "MALAT1 also contributes to enzalutamide resistance in castration-resistant prostate cancer, and a MALAT1 siRNA reduced growth of enzalutamide-resistant tumor xenografts." (PMID 37346034, 2023). "Herein, we show that oncogenic lncRNA, MALAT1 is frequently overexpressed in advanced stage prostate cancer and plays a crucial role in maintaining genomic integrity." (PMID 37812088, 2023). "MALAT1-silenced prostate cancer cells exhibited decreased cell proliferation compared with shSCRM cells, while the effect was more pronounced (∼80%) in olaparib-treated cells, indicating that MALAT1 depletion augments olaparib activity." (PMID 37812088, 2023). "In accord with this, MALAT1 depletion remarkably reduced 3D cell migration in 22RV1 (∼60%) and LNCaP (∼70%) cells compared with shSCRM controls, suggesting that MALAT1 is required for prostate cancer cell migration." (PMID 37812088, 2023). "As MALAT1 depletion markedly enhances cellular sensitivity to PARPi, we examined the effect of olaparib treatment on cell-cycle profiles in MALAT1-silenced prostate cancer cells by performing EdU staining." (PMID 37812088, 2023). "We showed that MALAT1 modulates DNA repair pathways and plays an essential role in maintaining genomic integrity in patients with advanced-stage prostate cancer." (PMID 37812088, 2023).
prostate carcinoma (continued). "Expression levels of PCA3 and MALAT1 in urinary exosomes have been shown to be superior to the currently used clinical parameters in detection of prostate cancer, particularly high-grade ones." (PMID 37025585, 2023). "On the basis of our in vitro results and previous research emphasizing the role of MALAT1 in prostate tumorigenesis and metastasis, we next examined the impact of PARPi in MALAT1-high versus low prostate cancer tumors." (PMID 37812088, 2023). "Surprisingly, miR-338–5p and miR-421, which we previously validated as tumor suppressor miRNAs in prostate cancer, were also present among the predicted miRNAs that interacted with MALAT1." (PMID 37812088, 2023). "A marginal increase in the early apoptotic cell population was observed in MALAT1-ablated prostate cancer cells compared with their respective shSCRM controls, while upon olaparib treatment the number of apoptotic cells was markedly increased." (PMID 37812088, 2023). "Contribution of single nucleotide polymorphisms (SNPs) within GAS5, POLR2E, MEG3, MALAT1 and HOTAIR in the risk of prostate cancer has been assessed in different ethnic groups." (PMID 37025585, 2023). "Collectively, these findings establish that MALAT1 acts as a master regulator that modulates HR, cell-cycle progression, and apoptosis in prostate cancer." (PMID 37812088, 2023). "MALAT1 also impacted castration‐resistant prostate cancer by interacting with EZH2 recruitment to its target loci." (PMID 35592755, 2022). "Existing evidence has further shown the binding of miR-1-3p to MALAT1 in prostate cancer cells, such that MALAT1 is capable of reducing the expression of miR-1-3p." (PMID 35813865, 2022). "We reveal that miR-423-5p directly interacts with MALAT1 and downregulates its expression in prostate cancer cells." (PMID 35016717, 2022). "In prostate cancer (PCa), MALAT1 plays a role in tumorigenesis and cancer progression and has been proposed as a potential therapeutic target for castration resistant PCa." (PMID 35016717, 2022). "Knockdown of MALAT1 inhibited the growth of prostate cancer both in vitro and in vivo, an effect that the authors suggest is brought about through sd/miR-140’s release from repression by MALAT1." (PMID 36009366, 2022). "As a consequence of the findings of bioinformatics investigations, lncRNA MALAT1 has been identified as a possible candidate in the development and progression of prostate cancer." (PMID 36163080, 2022). "We highlight the role of TRAMP mice as a model of studying MALAT1-driven prostate cancer and primary second-generation antiandrogen resistance." (PMID 35159020, 2022). "Overall, our findings demonstrate that miR-423-5p acts as a tumour suppressor by preventing prostate cancer cells’ proliferation, invasion and metastasis through mechanisms that involve, at least in part, the repression of MALAT-1 expression and functions." (PMID 35016717, 2022). "According to studies in this field, MALAT1 acts as an oncogene in prostate cancer cell lines, so its expression level is considerably higher in these cells." (PMID 36163080, 2022). "MALAT-1 was reported to maintain prostate tumorigenicity and involved in prostate cancer progression." (PMID 36033474, 2022). "Oppositely, MALAT1 overexpression conferred chemoresistance to prostate cancer cells against the cytotoxicity of quercetin." (PMID 35656022, 2022). "Downregulating the expression of MALAT-1 inhibits the migration, invasion, and growth of prostate cancer cells, increases the rate of apoptosis, and blocks the cell cycle." (PMID 35103065, 2022). "The expression level of MALAT1 was remarkably diminished in quercetin-treated prostate cancer cells." (PMID 35656022, 2022). "The MALAT1 lncRNA acts as an oncogene in Prostate cancer (PC); thus, it can be severe as a cancer biomarker." (PMID 36163080, 2022).
prostate carcinoma (continued). "Recently, in prostate cancer, MALAT1 was proposed to be a mediator of enzalutamide resistance through its indispensable role in AR-splice variant 7 (AR-V7) formation, and hence a potential target for pharmacological intervention in prostate cancer." (PMID 35159020, 2022). "We deeply characterized a frequently used mouse model of prostate cancer and found cellular and molecular regulators of resistance against antihormonal treatment, such as basal cell function and MALAT1 gene fusions." (PMID 35159020, 2022). "Mechanistically, MALAT1 promoted the EMT process in prostate cancer cells by upregulating N-cadherin and downregulating E-cadherin." (PMID 35656022, 2022). "Upregulation of MALAT‐1 is associated with tumor stage, high Gleason score PSA, and castration‐resistant prostate cancer, suggesting its strong therapeutic potential in prostate cancer." (PMID 35592755, 2022). "The overexpression of miR-423-5p inhibits MALAT1-mediated proliferation, migration, and invasion of prostate cancer cells." (PMID 35016717, 2022). "Recently, many ncRNAs, such as MALAT1, NEAT1, MIR25, and LET-7, are found to be associated with prostate cancer." (PMID 34576294, 2021). "For example, IL8 secreted from M2-polarized macrophages promotes prostate cancer progression via the STAT3/MALAT1 pathway, while knockdown of MALAT1 expression levels in prostate cancer cell lines inhibits cell proliferation, invasion and tumor formation." (PMID 34654454, 2021). "In a recent study, a long noncoding RNA associated with lung adenocarcinoma transcript 1 (MALAT1) is isolated from CORO1C; silencing of MALAT1 was shown to inhibit the migration, invasion, and epithelial-mesenchymal transition of prostate cancer cells." (PMID 34194957, 2021). "Three SNPs of MALAT1 were analyzed to identify the impacts of SNPs on the clinicopathologic features in Taiwanese prostate cancer." (PMID 34574033, 2021). "The lncRNA MALAT1 acts through the miR-145-5p/A-kinase anchoring protein 12 (AKAP12) axis to influence prostate cancer therapy." (PMID 34079751, 2021). "Meanwhile, some studies have demonstrated that the silencing of MALAT1 leads to a metabolic reprogramming in prostate cancer." (PMID 34574033, 2021). "Although urinary MALAT1 was identified as a potential biomarker of prostate cancer, its expression in urinary exosomes is still unclear." (PMID 34439239, 2021). "Although results obtained in the ex vivo model require validation in a larger cohort because of the limited number of samples evaluated, they indicate a relevant role played by MALAT1 in the metabolic reprogramming of prostate cancer cells." (PMID 33375130, 2020). "Altogether, these data suggest that MALAT1 acts as a critical metabolic controller of prostate cancer." (PMID 33375130, 2020). "Similar observations have been reported in CRC, esophageal carcinoma, gallbladder, cervical cancer, and prostate cancer where knockdown of MALAT1 abrogated tumor growth and/or metastasis in the respective cell line-derived models and/or PDX mouse models." (PMID 32503170, 2020). "For example, lncRNA MALAT1 is highly expressed in prostate cancer, which promotes the development of prostate cancer by activating EZH2." (PMID 31123170, 2019). "And the use of small interfering RNA knockdown MALAT1 in the treatment of enzalutamide (Enz)-resistant prostate cancer has also entered preclinical studies stage." (PMID 31391118, 2019). "We elucidated a novel reciprocal regulatory network between miR‐338‐5p/miR‐421 and MALAT1 in SPINK1 positive prostate cancer and a potential therapeutic modality." (PMID 29460395, 2018). "In sum, these data indicate that MALAT1 is a promising and useful biomarker for prostate cancer detection and warrants further study in clinical trials with a large sample size." (PMID 28272371, 2017).
prostate carcinoma (continued). "Initial studies using MALAT1 siRNAs demonstrated inhibition of cell migration, growth, and invasion in prostate cancer cells, while siRNAs directed against HOTAIR have been shown to reduce matrix invasion in breast cancer cells." (PMID 28829354, 2017). "MALAT1 has been demonstrated to promote lung, bladder, colorectal, liver, oral and prostate cancer cells proliferation and migration." (PMID 28615056, 2017). "In early studies, fragments from different regions of the MALAT-1 transcript were detected at higher copy numbers in the plasma of patients with prostate cancer than in non-prostate cancer patients." (PMID 27189224, 2016). "MALAT-1 expression has been found to be up-regulated in many solid tumors, such as lung, liver, and prostate cancers and has a tumor-promoting function." (PMID 27227769, 2016). "With a sensitivity and specificity of 58.6 % and 84.8 %, respectively, MALAT-1 has been proposed as a biomarker for prostate cancer diagnosis." (PMID 27189224, 2016). "Further studies will be required to elucidate the molecular mechanism by which MALAT1 regulates prostate cancer metastasis." (PMID 27600237, 2015). "Knocking down MALAT1 by siRNA in prostate cancer cell lines inhibited cell growth, invasion, and migration and induced cell cycle arrest in the G0/G1 phases." (PMID 27600237, 2015). "MALAT1 is an lncRNA previously shown to promote proliferation and invasion of many cancers, including prostate cancer." (PMID 27600237, 2015). "The long noncoding RNA MALAT1 was recently reported to maintain prostate cancer tumorigenicity and progression." (PMID 26110379, 2015). "MALAT1 is up-regulated in prostate cancer, and down-regulating it via siRNA attenuated prostate cancer cell growth, invasion and migration and induced CRPC cell cycle arrest in G0/G1 followed by concomitant prolongation of survival of tumor-bearing mice." (PMID 26110379, 2015). "We also identified osteoblastic Sost as a major regulator of PC3 gene expression and identified lncRNA MALAT1 as a target gene regulated by Sost in prostate cancer cells." (PMID 27600237, 2015). "Higher MALAT-1 expression is correlated with aggressive characteristics of PCa in prostate cancer tissue." (PMID 25526029, 2014). "Using RNA-Seq and quantitative RT-PCR, we found that MALAT-1 is upregulated in prostate cancer tissues compared with adjacent normal tissues and benign prostatic hyperplasia (BPH) tissues." (PMID 25526029, 2014). "Silencing of MALAT-1 by siRNA transfection inhibited cell growth, invasion and migration and induced cell cycle arrest in the G0/G1 phase in castration resistant prostate cancer." (PMID 25119862, 2014). "Very recently, it was shown that MALAT1 was detectable in plasma of patients with gastric or prostate cancer." (PMID 24313945, 2013). "MALAT1 overexpression was closely linked to epithelial-mesenchymal transition (EMT), as evidenced by decreased E-cadherin and increased vimentin expression in colorectal, breast, and prostate cancers." (PMID 40674376, 2025). "Moreover, HyPR-MS maps prostate cancer complexes (MALAT1/NEAT1/NORAD), while TOBAP-MS identifies HULC’s 140 interactors in liver cancer, and BioID-MS links HOTAIR to ribosomes in breast cancer cell lines." (PMID 40861865, 2025). "Furthermore, the expression of MALAT1 was considerably higher in hormone-resistant prostate cancer (CRPC) than in cases of prostate cancer that detect hormones." (PMID 39512820, 2024). "Aimy Sebastian investigated an in vitro co-culture model of PC3 prostate cancer cells and osteoblasts and found that reduced SOST expression in the tumor microenvironment may promote bone metastasis in prostate cancer through up-regulation of MALAT1." (PMID 38172792, 2024). "Thus, we demonstrated selective depletion of Malat1 lncRNA by mesyl or busyl ASO conjugates with a PSMA ligand in PSMA+/+ prostate cancer cells." (PMID 38501046, 2024).
prostate carcinoma (continued). "Furthermore, in the realm of therapeutic biomarkers, pre-clinical studies have demonstrated the efficacy of targeting MALAT-1 using RNA interference in prostate cancer, yielding successful results in xenograft models." (PMID 38095719, 2024). "Yadav and colleagues looked into the function of MALAT-1 in prostate cancer." (PMID 38511067, 2024). "Moreover, in vitro and in vivo studies have shown the importance of MALAT1/miR-140/BIRC6 axis in the progression of prostate cancer." (PMID 37025585, 2023). "Taken together, these results indicate that MALAT1 positively correlates with the clinicopathologic features of aggressive prostate cancer and may serve as a promising prognostic marker." (PMID 37812088, 2023). "Metastatic prostate cancer cells frequently acquire cancer stem cell (CSC) properties, which result in self-renewal and chemoresistance, therefore we examined the TCGA-PRAD cohort for any association of MALAT1 with self-renewal factors." (PMID 37812088, 2023). "Aimy Sebastian discovered that a lower SOST expression in the tumor microenvironment may enhance bone metastasis in prostate cancer via up-regulation of MALAT1 in an in vitro co-culture model of PC3 prostate cancer cells and osteoblasts." (PMID 37664033, 2023). "Likewise, a robust decrease in the expression of CD338 (ABCG2), an ATP-binding cassette transporter, was also noted in 22RV1 shMALAT1 cells compared with 22RV1-shSCRM, suggesting that MALAT1 modulates stemness in prostate cancer cells." (PMID 37812088, 2023). "This indicates that reduced Sost expression in the tumour microenvironment may promote bone metastasis by up-regulating MALAT1 in prostate cancer." (PMID 37143733, 2023). "Similarly, a strong positive correlation (ρ ≥ 0.4) between MALAT1 and cell cycle–associated genes was noted in prostate cancer patient specimens (GSE35988 and GSE3325), suggesting that MALAT1 plays a pivotal role in cell-cycle progression." (PMID 37812088, 2023). "Thus, we performed annexin-V and 7-AAD staining and noticed a robust increase in early apoptotic cells in MALAT1-depleted prostate cancer cells." (PMID 37812088, 2023). "In turn, expression and activity of MALAT1 have been shown to be regulated by miR-423-5p, a miRNA that impedes activity of MALAT1 in enhancement of proliferation, migration, and invasiveness of prostate cancer cells." (PMID 37025585, 2023). "To assess whether MALAT1 depletion impairs the DNA repair system and sensitizes prostate cancer to olaparib, we examined the frequency of γH2AX foci in olaparib-treated MALAT1-silenced cells." (PMID 37812088, 2023). "Conclusively, our findings indicate that oncogenic lncRNA MALAT1 protects prostate cancer tumor cells from anticancer agents by initiating the HR pathway, revealing a potential therapeutic vulnerability that can be exploited by targeting MALAT1 or overexpressing miR-421 in conjunction with PARPi." (PMID 37812088, 2023). "In addition, this study provides an important molecular connection between MALAT1, miR-421, and HR pathway in prostate cancer." (PMID 37812088, 2023). "Moreover, we show that miR-421, a tumor suppressor miRNA, negatively regulates the expression of HR genes, while in aggressive prostate cancer cases, miR-421 is sequestered by MALAT1, leading to increased expression of HR genes." (PMID 37812088, 2023). "Notably, a remarkable decrease in E2F1 levels was observed upon MALAT1 depletion in prostate cancer cells." (PMID 37812088, 2023). "As a common oncogene, MALAT‐1 also functioned in prostate cancer." (PMID 35592755, 2022). "The association between MALAT1 and EZH2 may provide a novel therapeutic strategy for management of many cancers, such as GC and prostate cancer." (PMID 36452326, 2022). "MALAT1 was also the target in preclinical studies with short interfering RNAs (siRNAs) to overcome the anti-androgen enzalutamide (Enz) resistance (EnzR) in castration-resistant prostate cancer." (PMID 36012617, 2022).